ACTR1A (actin related protein 1A)
Description:
Part of the ACTR1A/ACTB filament around which the dynactin complex is built. The dynactin multiprotein complex activates the molecular motor dynein for ultra-processive transport along microtubules.
Synonyms: CTRN1; ARP1; Arp1A
Tractability: PROTAC: ubiquitination databases record sites on it; its protein half-life has been measured.
Gene: Protein-coding gene on chromosome 10 (102,461,881 to 102,502,744, reverse strand). Ensembl gene ENSG00000138107.
Subcellular location: Cytoplasm, cytoskeleton; Cytoplasm, cytoskeleton, microtubule organizing center, centrosome; Cytoplasm, cell cortex
Subcellular location (Human Protein Atlas): Microtubules; Cytokinetic bridge; Cytosol; Primary cilium
Pathways (Reactome):
Cell Cycle: AURKA Activation by TPX2; Loss of Nlp from mitotic centrosomes; Loss of proteins required for interphase microtubule organization from the centrosome; Recruitment of NuMA to mitotic centrosomes; Recruitment of mitotic centrosome proteins and complexes; Regulation of PLK1 Activity at G2/M Transition
Vesicle-mediated transport: COPI-independent Golgi-to-ER retrograde traffic; COPI-mediated anterograde transport
Cellular responses to stimuli: HSP90 chaperone cycle for steroid hormone receptors (SHR) in the presence of ligand
Immune System: MHC class II antigen presentation
Organelle biogenesis and maintenance: Anchoring of the basal body to the plasma membrane
Gene Ontology:
Molecular function: protein binding; structural constituent of cytoskeleton
Biological process: vesicle-mediated transport; cytoskeleton organization
Cellular component: cell cortex; centrosome; cytoplasm; extracellular exosome; cytosol; dynactin complex; microtubule associated complex; cytoskeleton; microtubule organizing center
Genetic constraint (gnomAD): Loss-of-function variants: 10 observed, 50.33 expected, observed/expected ratio (o/e) 0.2, 90% interval 0.12 to 0.34. The upper end of that interval is the gene's LOEUF score, 0.34, which puts it in group 1 of 6, group 1 being the genes least tolerant of losing a copy. Missense variants: 250 observed, 502.68 expected, observed/expected ratio (o/e) 0.5, 90% interval 0.45 to 0.55. Synonymous variants: 177 observed, 191.69 expected, observed/expected ratio (o/e) 0.92, 90% interval 0.82 to 1.05.
Homologues: Orthologues: guinea pig ACTR1A (100% identical), macaque ACTR1A (100% identical), mouse Actr1a (100% identical), rat Actr1a (100% identical), dog ACTR1A (97% identical), rabbit ACTR1A (97% identical), pig ACTR1A (94% identical), tropical clawed frog actr1a (94% identical), zebrafish actr1b (93% identical), chimpanzee ACTR1A (91% identical), Drosophila melanogaster Arp1 (79% identical), Caenorhabditis elegans arp-1 (70% identical). Paralogues in human: ACTR1B (90% identical), ACTG1 (55% identical), ACTB (54% identical), ACTA2 (54% identical), ACTC1 (53% identical), ACTG2 (53% identical), ACTA1 (53% identical), ACTBL2 (51% identical), ACTR2 (43% identical), ACTRT3 (42% identical), ACTRT2 (41% identical), ACTR3 (40% identical), and 14 more.
Diseases named in the same sentence as ACTR1A in open-access papers:
ACTR1A is named in the same sentence as 8 diseases in open-access papers, as found by Europe PMC text mining. Sharing a sentence is not in itself a finding about the gene and the disease. The quoted sentences say what the papers report.
schizophrenia (3 papers, 2021 to 2025). A major psychotic disorder characterized by abnormalities in the perception or expression of reality. "Regarding intelligence and schizophrenia, MAAT identified 21 genes with high association levels in these two traits, where the significant function of ACTR1A, C22orf46, CKB, CYP2D6, LRRC37A, NCK1, and ZMAT2 have been well validated in large-scale GWAS studies." (PMID 39905509, 2025). "Here these two proteins, RAB6B and RAB7A, were found altered in the prefrontal cortex in schizophrenia with an interaction with both ACTR1A and DCTN5." (PMID 37033658, 2023). "Our analysis also found altered ACTR1A protein in the prefrontal cortex in schizophrenia." (PMID 37033658, 2023).
leprosy (1 paper, 2022). Leprosy is a chronic infectious disease affecting primarily the skin and peripheral nervous system. "The leprosy protective allele, rs2015583:G, is associated with reduced ACTR1A expression in CD4+ T cells (p = 4.69 × 10−9, β = −0.085)." (PMID 36121873, 2022). "We identify expression of ACTR1A in CD4+ T cells as candidate effector of leprosy risk at this locus." (PMID 36121873, 2022). "In CD4+ T cells the leprosy-associated locus is a determinant of ACTR1A expression, however in skin and peripheral nerves it determines TMEM180 expression." (PMID 36121873, 2022). "Using publicly-available data we characterise regulatory activity at this locus, identifying ACTR1A as a candidate mediator of leprosy risk." (PMID 36121873, 2022). "Taken together, chromatin state, eQTL mapping data and differential gene expression in the context of leprosy, identifies ACTR1A as a novel candidate mediator of leprosy susceptibility." (PMID 36121873, 2022). "To help address this ambiguity, we explored whether expression of ACTR1A or TMEM180 is associated with leprosy disease in previously-published transcriptomic studies." (PMID 36121873, 2022). "Having identified two distinct candidates in ACTR1A and TMEM180 for mediation of the leprosy risk effect at chromosome 10q24.32, we sought to explore the expression of both genes in the context of leprosy." (PMID 36121873, 2022). "To further explore the down-regulation of ACTR1A expression in leprosy skin lesions, we investigated the effect of subtype of clinical leprosy on ACTR1A expression in the same dataset." (PMID 36121873, 2022). "In comparison to healthy skin samples (n = 9), gene expression of ACTR1A is significantly down-regulated in skin lesions (n = 67) from patients with leprosy in Brazil (p = 0.0004)." (PMID 36121873, 2022). "One of the credible set SNPs we identify in the leprosy GWAS, rs2274351:T, is located in an active promoter at the 5’ ends of two genes (ACTR1A and SUFU)." (PMID 36121873, 2022). "In these data we again see significant down-regulation of ACTR1A expression in lesions of leprosy patients with tuberculoid disease compared to lepromatous disease (p = 0.0007)." (PMID 36121873, 2022). "In that analysis the down-regulation of ACTR1A expression in leprosy skin lesions compared to healthy controls is seen in tuberculoid (p = 0.0085) and borderline forms of leprosy (p = 0.0003), but not in lepromatous disease (p = 0.218)." (PMID 36121873, 2022). "Our leading candidate mediator of leprosy risk at 10q24.32, ACTR1A expression in CD4+ T cells, is highly biologically plausible as a determinant of leprosy." (PMID 36121873, 2022). "We then explored whether expression ACTR1A or TMEM180 was perturbed in leprosy skin lesions." (PMID 36121873, 2022). "To do this we downloaded publicly-available gene expression data in whole blood and skin from patients with leprosy and healthy controls, exploring evidence for differential expression of ACTR1A and TMEM180 in leprosy." (PMID 36121873, 2022).
cancer (1 paper, 2025). A tumor composed of atypical neoplastic, often pleomorphic cells that invade other tissues. "The hub genes ATP6AP2, ACTR1A, SYNM, ZMYND8, CAMTA1, SLC39A3, and DHCR24, are associated with cancer development and progression." (PMID 39757707, 2025).
ACTR1A also shares sentences with these, for which no sentence is quoted: asthma (1 paper); childhood onset asthma (1); depression (1); infection (1); tumor (1).